DDX43 (DEAD-box helicase 43)
Synonyms: CT13; HAGE; DKFZp434H2114
Tractability: PROTAC: ubiquitination databases record sites on it.
Gene: Protein-coding gene on chromosome 6 (73,394,828 to 73,417,566, forward strand). Ensembl gene ENSG00000080007.
Gene Ontology:
Molecular function: protein binding; RNA binding; RNA helicase activity; ATP binding; ATP hydrolysis activity; nucleic acid binding
Genetic constraint (gnomAD): Loss-of-function variants: 32 observed, 54.59 expected, observed/expected ratio (o/e) 0.59, 90% interval 0.44 to 0.79. The upper end of that interval is the gene's LOEUF score, 0.79, which puts it in group 3 of 6, group 1 being the genes least tolerant of losing a copy. Missense variants: 482 observed, 584.82 expected, observed/expected ratio (o/e) 0.82, 90% interval 0.76 to 0.89. Synonymous variants: 210 observed, 200.24 expected, observed/expected ratio (o/e) 1.05, 90% interval 0.94 to 1.18.
Homologues: Orthologues: chimpanzee DDX43 (99% identical), macaque DDX43 (97% identical), dog DDX43 (76% identical). Paralogues in human: DDX53 (59% identical), DDX5 (33% identical), DDX17 (32% identical), DDX46 (31% identical), DDX42 (29% identical), DDX23 (28% identical), DDX4 (28% identical), DDX3X (28% identical), DDX3Y (28% identical), DDX41 (27% identical), DDX21 (25% identical), DDX52 (25% identical), and 26 more.
Diseases named in the same sentence as DDX43 in open-access papers:
DDX43 is named in the same sentence as 30 diseases in open-access papers, as found by Europe PMC text mining. Sharing a sentence is not in itself a finding about the gene and the disease. The quoted sentences say what the papers report.
breast carcinoma (7 papers, 2016 to 2025). "DDX43 was shown to be overexpressed in breast cancer.its overexpression was linked to poor prognosis, aggressive clinical and pathological features in breast cancer patients." (PMID 37200388, 2023). "Finally, the possible protein interacting networks of DDX43 together with the underlying molecular mechanisms in breast cancer were elucidated using bioinformatics analyses only." (PMID 37200388, 2023). "Since breast cancer patients have lower blood levels of DDX43 gene expression relative to normal subjects, this may be due to DDX43 gene mutation in breast cancer." (PMID 37200388, 2023). "This proposes that lower serum DDX43 protein levels may be linked to types of breast cancer with a bad prognosis or with a poor prognosis." (PMID 37200388, 2023). "On the other hand, high DDX43 mRNA expression levels in these patients may be linked to the higher tumor and nuclear grades or aggressive types of breast cancer as TNBC." (PMID 37200388, 2023). "More immunohistochemistry studies, larger validation studies, in vitro and in vivo tests are needed to validate the influence of DDX43 expression on human breast cancer pathogenesis and its worth in prognosis and gene therapy." (PMID 37200388, 2023). "It showed low staining of DDX43 protein in breast cancer tissues like serum DDX43 protein level in malignant breast cancer patients stated in the current study." (PMID 37200388, 2023). "In contrast to the documented overexpression of DDX43 in breast cancer tissues and other cancer types, the current investigation found that DDX43 is probably under expressed in the blood of malignant BC patients compared to benign BC and control subjects." (PMID 37200388, 2023). "We have found that DDX43 expression in the blood of malignant breast cancer patients is under-expressed." (PMID 37200388, 2023). "This study explored the potential of using blood DDX43 mRNA expression or protein levels, or both in clinical settings as a marker of disease progression in human breast cancer." (PMID 37200388, 2023). "DDX43 (also known as HAGE) had been reported as a promising biomarker indicated poor prognosis in breast cancer." (PMID 35237592, 2022). "The expression of DDX43 is a potential prognostic marker and a predictor of response to anthracycline treatment in breast cancer." (PMID 33199368, 2021). "As we know, DDX43 mRNA expression in breast cancer patients has been studied before." (PMID 37200388, 2023). "In particular, CpGs located in the DDX43 gene, which are involved in spermatogenesis and male fertility, or CpG located in the GABPA gene, are associated with early onset Alzheimer’s disease, Parkinson’s disease, and breast cancer." (PMID 38053163, 2023). "Thus, DDX43 mRNA expression or serum protein levels, or both have the potential to be used as markers of disease progression in human breast cancer." (PMID 37200388, 2023). "In malignant cases, low DDX43 protein expression was linked to higher nuclear grade and invasive duct carcinoma (IDC), whereas high mRNA expression was linked to the aggressive types of breast cancer such as TNBC, higher tumor and nuclear grades." (PMID 37200388, 2023). "Another explanation for the down-regulation of DDX43 gene expression in the blood of breast cancer patients may be attributable to low Mg2+ levels in the selected cancer patients." (PMID 37200388, 2023). "DDX43 (also named HAGE), belonging to the DEAD-box helicase subfamily, is a potential prognostic marker in patients with breast cancer." (PMID 41157636, 2025).
melanoma (6 papers, 2012 to 2025). A malignant, usually aggressive tumor composed of atypical, neoplastic melanocytes. "DDX43 expression promotes melanoma tumor growth and progression." (PMID 33199368, 2021). "DDX43 regulates RAS protein expression and AKT activation, prevents the expression of PML in ABCB5+ malignant melanoma-initiating cells, and plays a critical role in the male sex differentiation of channel catfish (Ictalurus punctatus)." (PMID 41157636, 2025). "A second helicase, recently shown to be expressed in a subpopulation of melanoma cells, referred to as ABCB5+ malignant melanoma-initiating cells, is HAGE (alias Cancer/testis antigen 13 (CT13); DDX43)." (PMID 23116066, 2012).
acute myeloid leukemia (5 papers, 2017 to 2024). Acute myeloid leukemia (AML) is a group of neoplasms arising from precursor cells committed to the myeloid cell-line differentiation. "Aberrant DNA methylation status in the DDX43 promoter is known to be associated with human cancers including acute myeloid leukemia." (PMID 35144563, 2022). "DDX43 expression is increased in 50% of acute myeloid leukemia cases and high expression will activate the Ras signaling pathway thus promoting cell proliferation." (PMID 28243201, 2017). "In hematologic malignancies, DDX43 is overexpressed in acute myeloid leukemia (AML), CML, multiple myeloma and a variety of malignant cell lines derived from B or T lymphocytic cells." (PMID 29449695, 2018). "DDX43 is also overexpressed in more than 50% of chronic myeloid leukemia (CML) cases, 20% of acute myeloid leukemia cases, and more than 40% of multiple myeloma cases." (PMID 33199368, 2021). "Frequent high expression of DDX43 was also found in CML and acute myeloid leukemia." (PMID 33199368, 2021).
chronic myeloid leukemia (3 papers, 2018 to 2024). "DDX43 has been identified as being overexpressed in a range of solid tumors including those affecting the salivary gland, colon, brain, lung, and prostate, as well as in hematologic malignancies like chronic myeloid leukemia and multiple myeloma." (PMID 38807916, 2024). "In the present study, we explored the function of DDX43 in chronic myeloid leukemia (CML)." (PMID 29449695, 2018).
leukemia (3 papers, 2017 to 2019). A malignant (clonal) hematologic disorder, involving hematopoietic stem cells and characterized by the presence of primitive or atypical myeloid or lymphoid cells in the bone marrow and the blood. "Hypomethylation of DDX43 induces the expression of the gene and is strongly correlated with advanced disease and poor prognosis in leukemia." (PMID 28243201, 2017). "The axis of DDX43/H19/miR‐186 may be an attractive candidate for overcoming drug resistance in leukemia therapy." (PMID 30793488, 2019).
sarcoma (2 papers, 2021 to 2023). A usually aggressive malignant neoplasm of the soft tissue or bone. "One such KH domain–containing helicase is DDX43, also known as HAGE (helicase antigen gene), which was first identified as a cancer/testis antigen gene in a human sarcoma cell line." (PMID 33199368, 2021). "In a human sarcoma cell line, researchers found the cancer/testis antigen gene DDX43, commonly known as HAGE (helicase antigen gene)." (PMID 37200388, 2023).
Infertility (1 paper, 2023). "The loss of its ATP hydrolysis activity by a missense mutation replicates the infertility phenotype in global Ddx43 knockout mice." (PMID 37120627, 2023).
male infertility (1 paper, 2023). The inability of the male to effect fertilization of an ovum after a specified period of unprotected intercourse. "Here, we show that genetic mutation of Ddx43 leads to defects in developing spermatids, failure to produce mature spermatozoa, and male infertility." (PMID 37120627, 2023). "Testis-specific Ddx43 knockout mice show male infertility with defective histone-to-protamine replacement and post-meiotic chromatin condensation defects." (PMID 37120627, 2023).
myeloid leukaemia (1 paper, 2021). "Many cancers, including myeloid leukaemia express the cancer testis antigen (CTA) DDX43 (HAGE) and/or the oncogene Wilms’ tumour (WT1)." (PMID 34262856, 2021).
seminoma (1 paper, 2016). A radiosensitive malignant germ cell tumor found in the testis (especially undescended), and extragonadal sites (anterior mediastinum and pineal gland). "DDX43 was heavily methylated in all samples other than seminoma while TDRD12 was methylated in all samples except seminoma and teratoma." (PMID 29263807, 2016). "DDX43 and TDRD12 were specifically hypomethylated in seminoma cells." (PMID 29263807, 2016).
viral infections (1 paper, 2025). "Given that various members of the DDX family (including, but not limited to, DDX3, DDX5, and DDX56) exhibit distinct regulatory effects on different viral infections, further studies are warranted to determine whether DDX43 exerts a proviral or antiviral effect on other viruses." (PMID 41157636, 2025). "As a member of the DDX family, the role of DDX43 in viral infections has not been reported." (PMID 41157636, 2025).
cancer (15 papers, 2016 to 2024). A tumor composed of atypical neoplastic, often pleomorphic cells that invade other tissues. "Similar to DNMT3A R882H mutation, DDX43 has been shown to be involved in tumor cell development in many types of cancers." (PMID 38807916, 2024). "Cancer-specific antigens, DDX43 (helicase antigen gene, HAGE) and DDX53 (cancer-associated gene, CAGE), are overexpressed in almost all cancers, while DDX20 (dp103) is highly expressed in breast cancer." (PMID 36761420, 2022). "While the DDX43 gene has been proposed as a possible oncogene because of its high expression in various types of cancer, details about its precise physical function are scarce." (PMID 37200388, 2023). "DDX43 is overexpressed in a variety of cancers and thus can serve as a biomarker and a possible drug-target molecule." (PMID 33199368, 2021). "High levels of DDX43 overexpression in various tumors suggest it is a potential target molecule for cancer therapy." (PMID 33199368, 2021). "EDIL3 and DDX43 were the most significantly upregulated genes in patients with high metastatic burden, whereas the cancer-testis (CT) antigens, such as MAGEA1, were found to show reduced expression in these patients." (PMID 32847064, 2020). "DDX43 (also known as HAGE) is initially found as a cancer/testis antigen overexpressed in many solid tumors but absent in normal tissues except testis, which indicates this gene has highly tissue-specific expression." (PMID 29449695, 2018). "A total of three differentially hypermethylated genes (CCNE1, PON3, and CCNDBP1) and two differentially hypomethylated genes (DDX43 and CHL1) were selected for the validation based on their β-value and association with CRC as well as other cancers." (PMID 28243201, 2017). "DDX43, also known as helicase antigen (HAGE), is responsible for cell proliferation and has a high expression level in cancer compared to normal." (PMID 28243201, 2017).
tumor (9 papers, 2012 to 2025). "This supports that higher DDX43 mRNA expression in some malignant BC patients is linked to higher tumor grades." (PMID 37200388, 2023). "All support that higher DDX43 mRNA expression may be linked to higher mitosis scores, higher nuclear grades, and smaller tumor size." (PMID 37200388, 2023). "In mammals, DDX43 plays an important role in the malignant proliferation and immune response of tumor cells." (PMID 41157636, 2025). "DDX43 was first identified together with sarcoma antigen (SAGE) as a tumor-specific CTA gene in a human sarcoma cell line." (PMID 38807916, 2024). "Whereas the mean normalized serum level of DDX43 protein was significantly lower in patients with tumor size (T3-4) than tumor size (T2), (p = 0.039)." (PMID 37200388, 2023). "While the mean normalized serum level of DDX43 protein was lower in the ILC tumor type than in the ICC tumor type but the result was marginally significant (p = 0.152)." (PMID 37200388, 2023). "The mean normalized serum level of DDX43 protein was higher in patients with tumor size (T2) than tumor size (T1), but the result was marginally significant (p = 0.058)." (PMID 37200388, 2023). "The mean normalized serum DDX43 protein level was higher in patients with tumor size (T2) than tumor size (T1), but the result was marginally significant." (PMID 37200388, 2023). "DDX43 protein was found in a range of tumor tissues, which include the brain, bladder, esophagus, colon, breast, stomach, small intestine, lung, liver, and kidney, while not in normal tissues or at extremely low levels, according to this study." (PMID 37200388, 2023). "The mean normalized level of DDX43 mRNA expression was considerably higher in tumor grade 3 than tumor grade 2, (p = 0.037)." (PMID 37200388, 2023). "As well, the mean normalized level of DDX43 mRNA expression was lower in patients with tumor size (T2) and (T3-4) than tumor size (T1), but the result was marginally significant (p = 0.110, p = 0.141)." (PMID 37200388, 2023). "Whereas the mean normalized serum level of DDX43 protein was significantly lower in patients with tumor size (T3-4) than in tumor size (T2)." (PMID 37200388, 2023). "The mean normalized serum DDX43 protein level was significantly lower in the IDC tumor type than in both ILC and ICC tumor types." (PMID 37200388, 2023). "As well, the mean normalized level of DDX43 mRNA expression was lower in patients with tumor size (T2) and (T3-4) than in tumor size (T1), but the result was marginally significant." (PMID 37200388, 2023). "DDX43 expression in tumor was detected by western blot, which showed that DDX43 was highly expressed in the DDX43-K562 group." (PMID 29449695, 2018). "In addition, in tumor grade 3 the mean normalized level of DDX43 mRNA expression was higher than in tumor grade 1, but the result was marginally significant (p = 0.056)." (PMID 37200388, 2023). "At the protein level, DDX43 has also been detected at different levels in a variety of tumor tissues including the bladder, brain, breast, colon, esophagus, kidney, liver, lung, stomach, and small intestine, whereas none or very little protein was found in the normal tissues." (PMID 33199368, 2021). "Thus, tumor size T1 may correlate to poor clinical outcome or worse prognosis which could explain the lower serum DDX43 protein level." (PMID 37200388, 2023). "The noticeable inconsistency between the behaviors claimed DDX43 to promote tumor growth versus the present study results that revealed higher DDX43 protein and mRNA expression blood levels in both control and benign groups than in malignant group might be explained in a variety of ways." (PMID 37200388, 2023). "The mean normalized serum level of DDX43 protein was significantly lower in the IDC tumor type than in both ILC and ICC tumor types (p = 0.042, p = 0.006)." (PMID 37200388, 2023).
tumor (continued). "DDX43, also known as Helicase Antigen Gene (HAGE), is highly expressed in the testes and is also upregulated in multiple tumours of various tissues, with negligible expression in normal tissues." (PMID 35769258, 2022). "Mostly, this is because all these studies assessed DDX43 protein expression in tumor tissues, not in blood or serum." (PMID 37200388, 2023).
hematological malignancies (1 paper, 2024). "Given the frequent studies reporting the hypomethylation of DDX43 promoter in hematological malignancies, and the significance of R882H mutations in DNMT3A, we hypothesized that there may be some relations between these two events." (PMID 38807916, 2024).
infection (1 paper, 2025). The state of being infected such as from the introduction of a foreign agent such as serum, vaccine, antigenic substance or organism. "The mRNA level of DDX43 exhibited a progressive increase in HeLa cells, while it gradually declined in ARPE-19 cells during the course of infection, consistent with the initial transcriptome sequencing results." (PMID 41157636, 2025).
DDX43 also shares sentences with these, for which no sentence is quoted: esophageal squamous cell carcinoma (2 papers); lung carcinoma (2); periodontitis (2); Alzheimer disease (1); colorectal cancer (1); gastric cancer (1); head and neck squamous cell carcinoma (1); hepatocellular carcinoma (1); invasive ductal carcinoma (1); multiple myeloma (1); oral squamous cell carcinoma (1); osteosarcoma (1); ovarian carcinoma (1); Parkinson disease (1); teratoma (1).